SNORD3E (small nucleolar RNA, C/D box 3E)
Gene: Small nucleolar RNA gene on chromosome X (70,846,080 to 70,846,295, reverse strand). Ensembl gene ENSG00000280704.
Gene Ontology:
Biological process: RNA processing
Cellular component: nucleolus
Homologues: Orthologues: chimpanzee U3 (100% identical), macaque U3 (28% identical). Paralogues in human: SNORD3P1 (86% identical), SNORD3D (81% identical), U3 (81% identical), SNORD3G (81% identical), U3 (80% identical), U3 (79% identical), SNORD3H (78% identical), U3 (77% identical), U3 (76% identical), U3 (75% identical), U3 (74% identical), U3 (73% identical), and 9 more.